APOE (apolipoprotein E)
Diseases named in the same sentence as APOE in open-access papers (continued):
Sharing a sentence is not in itself a finding about the gene and the disease.
atherosclerosis (continued). "Enhancing miR-27a/b function protected apoE KO mice from atherosclerosis as a result of obvious reduction of the expression of LPL, lipid uptake, and pro-inflammatory cytokine secretion, but inhibition of miR-27a/b function had the opposite effects." (PMID 27257686, 2016). "As such, age-matched atherosclerosis-resistant ApoE+/− littermates were used as controls to account for age-related metabolic changes." (PMID 27721472, 2016). "Further studies in a murine model of atherosclerosis demonstrated that plasma TMAO levels in apoE−/− mice positively correlated with atheroma burden." (PMID 27834801, 2016). "To assess the role of IR isoforms and IGF-IR in experimental atherosclerosis, we used ApoE−/− mice at 8, 12, 18 and 24 weeks of age." (PMID 27905925, 2016). "This study investigated the effect of Angpt2 on AAA development and atherosclerosis in the ApoE−/− mouse model." (PMID 27767064, 2016). "Most of the key intermediate metabolites involved in these metabolisms were significantly altered between the three stages of atherosclerosis observed in ApoE−/− mice." (PMID 27721472, 2016). "Inhibition of 11β-HSD1 in atherosclerosis-prone apoE KO mice directly attenuates atherosclerotic plaques and decreases pro-inflammatory gene expression in the vasculature." (PMID 28018358, 2016). "At the same time, our results have shown a positive effect of miR-27 on the pathological process of atherosclerosis through reducing accumulation of intracellular lipids and secretion of pro-inflammatory cytokines in apoE KO mice." (PMID 27257686, 2016). "The same group demonstrated a dose-dependent reduction in atherosclerosis in Tie1-attenuated ApoE−/− mice, giving credence to the idea that Tie1 is a critical regulator of the endothelial response to disturbed shear stress." (PMID 27027326, 2016). "We have previously characterized the WSS profiles in this ApoE−\− mouse model of disturbed flow-induced atherosclerosis ex vivo, demonstrating low WSS in the upstream segment and low and oscillatory WSS in the downstream segment." (PMID 27853578, 2016). "Apolipoprotein E knockout (ApoE−/−) mice, a model of atherosclerosis, are sensitive to collagen‐induced arthritis (CIA)." (PMID 26859834, 2016). "To assess PIAS3 expression and its correlation with atherosclerosis development, we fed wild-type (WT) mice and ApoE−/− mice chow or western diets for 20 weeks." (PMID 27845432, 2016). "We initially verified that hypoxia was present in atherosclerotic plaques of HFD-fed end.SclCreERT;R26RstopYfp;ApoE−/− mice, finding that with progressive atherosclerosis there is a marked increase in the percentage of hypoxic cells in intimal plaques." (PMID 27340017, 2016). "To investigate the underlying mechanisms of ISL on atherosclerosis and hepatic steatosis, we examined the effects of ISL on the hepatic expression of lipoprotein-metabolism-related genes in apoE−/− mice." (PMID 27869741, 2016). "Ex vivo SPECT experiments revealed displaceable accumulation in atherosclerotic plaques of ApoE KO mice fed an atherosclerosis-promoting diet." (PMID 26728358, 2016). "For example, Cav-1-/- mice crossed with ApoE-/- mice were protected from high fat-diet induced atherosclerosis, instead forming fewer and smaller plaques than ApoE-/- mice." (PMID 26891050, 2016). "Nasal immunization with the OMP of Porphyromonas gingivalis was previously shown to be protective against accelerated atherosclerosis induced by intraperitoneal inoculation of bacteria in ApoE−/− mice." (PMID 27383250, 2016).
atherosclerosis (continued). "The present study was designed to investigate the impact of high-fat diet on ApoE(−/−) mice exhibiting atherosclerosis by detecting the genome-wide expression profile of lncRNAs and mRNAs." (PMID 27698357, 2016). "In this study, we investigated the direct effect of C5a overexpression on the development of atherosclerosis in ApoE−/− mice." (PMID 27517153, 2016). "After above in vitro experiments, the effects of EZH2 on the atherosclerosis were examined in six-week-old male apoE−/− mice." (PMID 27295295, 2016). "Thus, the present study was undertaken to elucidate whether intake of a Western-type diet with a mixture of cod and scallop protein, as compared to chicken fillet, would prevent development of CVD in the atherosclerosis-prone model Apolipoprotein E-deficient (apoE−/−) mice." (PMID 26839578, 2016). "In ApoE mice, SR‐A1 knock‐down reduces the generation of foam cells and atherosclerosis progression." (PMID 26493158, 2016). "We next analysed the effect of Adamts4 knockout on high fat diet induced atherosclerosis in ApoE−/− mice." (PMID 27491335, 2016). "A further limitation is the use of healthy young adult mice in these types of study, whereas older mice with atherosclerosis (e.g. ApoE mutant mice) would provide a more clinically relevant study population." (PMID 27882341, 2016). "In summary, our results show that compound K, an active monomer of Panax notoginseng saponins, attenuates the atherosclerosis formation in apoE−/− mice, through RCT promotion and inflammasome inhibition in association with LXRα activation." (PMID 27399689, 2016). "As a model for a murine atherosclerotic disease model, ApoE−/− mice were used to evaluate the effects of lanatoside C on the development of atherosclerosis." (PMID 26821916, 2016). "Further investigations using ApoE null mice with either constitutive expression or knockout of the fibronectin EDA domain showed that EDA+FN promotes progression of atherosclerosis through a mechanism that is partially dependent on TLR4." (PMID 27795867, 2016). "ApoE−/− mice start to develop atherosclerosis lesions from stage II while having been fed the Western diet for 8–10 weeks, with the mice being started on the diet when they are between 4–8 weeks old." (PMID 27187431, 2016). "The presence of arthritis did not exacerbate serum cholesterol levels or significantly augment the level of atherosclerosis in ApoE−/− mice." (PMID 27287704, 2016). "Given that ApoE−/− mice demonstrate the atherosclerosis phenotype, we further performed immunostaining to analyze expression of Nkx2‐5 in diseased ApoE−/− mice and normal C57BL/6 mice." (PMID 27993833, 2016). "Similar lysosomal pH effects have been reported in mouse peritoneal macrophages exposed to oxLDL and in macrophages isolated from the lesions of atherosclerosis-prone apoE-/- mice." (PMID 27997605, 2016). "ApoE-KO mouse fed with high cholesterol diet would result in severe atherosclerosis, leakage of blood-brain barrier, neuronal apoptosis and cognitive impairment." (PMID 27965573, 2016). "To confirm the cellular events in vivo, we prepared a chronic atherosclerosis model in ApoE KO and Nox4ApoE DKO mice on a HFD for 12 weeks with or without rFliC." (PMID 27146088, 2016). "For example APOE deficient mice are prone to atherosclerosis, but C3 modulation of lipid metabolism can protect them, while VEGFC is a marker for advanced atherosclerosis and hypercholesterolemia in the same animals." (PMID 27112350, 2016). "To further investigate the roles of miR-27a/b in the development of atherosclerosis in apoE KO mice fed high-fat diet, we measured the atherosclerotic lesion areas by an en face analysis of the whole aorta and the cross-sections of the aortic root." (PMID 27257686, 2016). "25, a diet high in cholesterol plus calcium markedly induced calcification, as well as atherosclerosis in ApoE KO mice." (PMID 26832969, 2016).
atherosclerosis (continued). "A mouse model of atherosclerosis with circadian clock genes expression disorder was established using ApoE-KO mice (ApoE-KO LD/DL mice) by altering exposure to light." (PMID 27631008, 2016). "Such treatment inhibits injury-induced hypertrophy in human and rodent vessels, and decreases atherosclerosis in ApoE knockout mice." (PMID 27213333, 2016). "To study the role of IR isoforms and IGF-IR in experimental atherosclerosis, we used ApoE−/− mice at 8, 12, 18 and 24 weeks of age." (PMID 27905925, 2016). "POLG−/−/ApoE−/− mice had increased atherosclerosis in the brachiocephalic artery and descending aorta as compared to POLG+/+/ApoE−/− controls." (PMID 27213333, 2016). "In apoE−/− mice, this process bears much resemblance to spontaneous atherosclerosis in terms of both etiology and pathogenesis." (PMID 28155719, 2016). "We suggest that ISL performs regulation of lipogenesis and also contributes to diminished hepatic steatosis and attenuated atherosclerosis in Western-diet-fed apoE−/− mice." (PMID 27869741, 2016). "In contrast, Cav‐1/ApoE double KO mice, with a > 2‐fold increase in LDL‐C 20, were protected from atherosclerosis, despite hypercholesterolaemia, underlying the role of CAV‐1 in transcytosis of LDL‐C across endothelial cells." (PMID 28149711, 2016). "IL-33 induced Th2 cytokines and Th2 antibodies in serum and lymph node cells of ApoE (−/−) mice, which was a classic murine model of atherosclerosis." (PMID 27172901, 2016). "We then advanced our analysis to examine the development of atherosclerosis by crossing Vash1(−/−) and ApoE(−/−) mice." (PMID 27325558, 2016). "This conclusion has been substantiated by the observation that macrophage-specific expression of human LPL promotes the development of atherosclerosis in apoE knockout mice and rabbits." (PMID 27257686, 2016). "ApoE-KO mice fed with high cholesterol diet resulted in severe atherosclerosis, increased leakage of blood-brain barrier, neuronal apoptosis, and cognitive impairment." (PMID 27965573, 2016). "In the present study, we explored the therapeutic potential of mitochondrially-targeted esculetin in mitigating oxidant-induced endothelial cell death and subsequently its effect in regressing Ang-II-induced atherosclerosis in ApoE−/− mice." (PMID 27063143, 2016). "This study confirms our previous results observed in older DKO animals, highlighting the early age of atherosclerosis in ApoE KO and het mouse models." (PMID 28149711, 2016). "To determine the effect of C5a gene transfer on the ability of the high-fat diet to induce atherosclerosis in ApoE−/− mice, we infused a subset of mice fed a high fat diet for 8 weeks with PBS, Ad-GFP, Ad-C5a, or Ad-C5a plus AcF [OPdChaWR]." (PMID 27517153, 2016). "In conclusion, VSL#3 reduced biomarkers of vascular inflammation and development of atherosclerosis to comparable extent as the positive control drug, telmisartan in ApoE−/− mice." (PMID 27576894, 2016). "The observed separation trend was consistent with the progression of atherosclerosis in ApoE−/− mice from pre-stage I to stage I and stage II of atherosclerosis." (PMID 27721472, 2016). "The current study now identifies the restoration of the eNOS/NO pathway as a major mechanism supporting the effects of dual inhibition of TxAS and TP receptor blockade in ApoE-KO mice at early stage of atherosclerosis." (PMID 27019366, 2016). "We were interested to know if reduced expression of PDE3B will help in moderation of atherosclerosis in apoE−/−and LDL-R−/−mice." (PMID 27321128, 2016). "In the cardiovascular system, CCR9 was first found to be associated with the pathophysiology of atherosclerosis, and inhibition of CCR9 by RNA interference in apoE-deficient mice significantly retarded the development of atherosclerosis." (PMID 27585634, 2016).
atherosclerosis (continued). "To investigate if ADAMTS4 accumulation in plaques correlates with the progression of atherosclerosis in ApoE−/− mice, we analysed ADAMTS4 expression in plaques by immunohistochemistry (IHC)." (PMID 27491335, 2016). "To clarify the role of ADAMTS4 in atherosclerosis, we generated double knockout mice (ApoE−/−Adamts4−/−) by crossing Adamts4−/− mice with ApoE−/− mice (both in C57Bl/6J background)." (PMID 27491335, 2016). "ApoE−/− mice fed a western diet have increased atherosclerosis with low dose IFNγ treatment (Bluyssen and Poledne 2015, unpublished results)." (PMID 27166190, 2016). "We therefore investigated the impact of caspase-3 deletion on atherosclerosis by crossbreeding caspase-3 knockout (Casp3−/−) mice with apolipoprotein E knockout (ApoE−/−) mice." (PMID 27847551, 2016). "In keeping with this, in a double knockout mouse model for PTX3 and apolipoprotein E (ApoE), macrophages infiltration was enhanced, and a dramatic increase of atherosclerosis was reported." (PMID 27559355, 2016). "Lanatoside C dose-dependently aggravated the development of atherosclerosis in the ApoE–/– mice compared with the vehicle control group." (PMID 26821916, 2016). "It has been demonstrated that hyperlipidemia and atherosclerosis in apolipoprotein E knockout (ApoE-KO) mice resulted in structural and functional changes in the inner ear, which were associated with hearing loss in a time-dependent manner." (PMID 27051663, 2016). "The role of P-selectin in the spontaneous development of advanced atherosclerosis was also evaluated in ApoE−/− mice." (PMID 27618031, 2016). "In a series of animal experiments, apolipoprotein E knockout mice (ApoE−/− mice) was used as the animal model for establishing the atherosclerosis model." (PMID 27187431, 2016). "Previous studies have demonstrated that important roles of diet in the formation of atherosclerosis in ApoE(−/−) mice." (PMID 27698357, 2016). "To assess the potentially atherosclerosis-promoting effects of lanatoside C on lipid metabolism, we monitored plasma lipids in ApoE–/– mice during the treatment period." (PMID 26821916, 2016). "These mice are less hyperlipidemic than ApoE−/− mice, spontaneously develop atherosclerosis when fed the atherogenic diet, and are suitable for exploring the mechanisms by which apolipoprotein E isoforms influence hepatic VLDL metabolism in atherogenesis." (PMID 27618031, 2016). "The present study was designed to evaluate the beneficial effects of BM-573, a dual TxAS inhibitor and TP receptor antagonist, on the vasodilatory function and blood pressure in ApoE-KO mice at early stage of atherosclerosis." (PMID 27019366, 2016). "Since female mice, at least on an ApoE–/–background, develop atherosclerosis more rapidly than males, we fed female transplant recipients a WTD for 13 weeks and male recipients a WTD for 19 weeks." (PMID 27223895, 2016). "The strongest experimental evidence that angiogenesis plays a pathogenetic role in atherosclerosis was derived from studies in the ApoE−/− mouse model." (PMID 27618031, 2016). "The atherosclerosis in this model is accelerated with high fat diet and similar models in the apoE −/− background are previously reported." (PMID 26778898, 2015). "Apolipoprotein E deficiency (ApoE−/−) combined with a high-fat Western-type diet (WD) is known to activate the toll-like receptor (TLR4) pathway and promote atherosclerosis." (PMID 25975841, 2015).
atherosclerosis (continued). "Genetic deletion of CCR2 or CCR5 in ApoE knockout mice significantly reduces atherosclerosis and monocyte mobilization." (PMID 25852821, 2015). "In the present study, we investigated the progression of atherosclerosis by examining inflammation in apolipoprotein E-deficient mice (APOE KO) following delivering MEF2A shRNA and found that silencing MEF 2A accelerates atherosclerosis." (PMID 25793529, 2015). "To determine if the reduced development of atherosclerosis in ApoE/mdx mice involved changes in vascular inflammation we analysed the macrophage and T cell accumulation in plaques from the low and oscillatory shear stress region of the carotid artery." (PMID 26345322, 2015). "Our results indicated that CUMS apoE-/- mice treatment with siRNA TLR4 significantly decreased atherosclerosis and down-regulated TLR4, NF-κB, and inflammatory cytokines." (PMID 25860573, 2015). "Accordingly, knockout of CD36 in proatherogenic ApoE-null mice protects the development of atherosclerosis lesions in these animals." (PMID 26557864, 2015). "Accordingly, EC-specific conditional deletion of Tie1 limited vascular inflammation and the development of atherosclerosis in ApoE-/- mice." (PMID 26436659, 2015). "We adopted the semi-automated knowledge extraction workflow and modeled causal and correlative relationships extracted from original scientific publications focused on plaque development and destabilization using the ApoE−/−model of atherosclerosis." (PMID 26200752, 2015). "Apolipoprotein E (apoE) is a component of triglyceride-rich lipoproteins and plays a major role in limiting atherosclerosis." (PMID 26068461, 2015). "Induction of diabetes with streptozotocin (STZ) in different atherosclerosis models, and especially in ApoE−/− mice, has been widely used to study the effects of therapeutic agents or the mechanisms of accelerated atherosclerosis." (PMID 25785279, 2015). "Taken together, these results indicated that APN derived from PVAT restricted atherosclerosis development in ApoE-/- mice, but didn’t affect atherosclerotic plaque disruption." (PMID 26020520, 2015). "There is compelling evidence that apolipoprotein E deficiency (ApoE−/−) combined with a high-fat diet regulates toll-like receptor 4 (TLR4) expression and promotes atherosclerosis development." (PMID 25975841, 2015). "We further found that the 9-cis β-carotene rich diet lowered plasma cholesterol levels and inhibited atherosclerosis progression in high-fat diet fed apoE-/- mice, with established atherosclerotic lesions." (PMID 25629601, 2015). "In the present study, we aim to examine the effect of BSN723T, a combination of D-tagatose and dihydromyricetin, on blood lipids and atherosclerosis in ApoE-/- knockout mice." (PMID 27683620, 2015). "While most of the evidence so far is from studies using nondiabetic ApoE−/−, there is limited data on the effects of incretin-based therapies on atherosclerosis in diabetic ApoE−/− mice." (PMID 25785279, 2015). "To understand the role of p47phox in the formation of atherosclerosis lesion in apoE(-/-) mice, we detected the mRNA and protein levels of p47phox in cultured primary AFs derived from apoE(-/-) mice." (PMID 25628043, 2015). "The data presented here provide the first evidence that high-level hepatic expression of hMsrA, achieved by lentiviral injection, resulted in diminished hepatic steatosis and attenuated atherosclerosis in Western-diet-fed apoE−/− mice." (PMID 26318157, 2015). "The extent of atherosclerosis in aorta of apoE−/− mice in AsIV group was significantly lighter than that in model group, and the SDF-1 and CXCR4 expression of aorta reduced, showing statistical significance (P < 0.05)." (PMID 26074989, 2015). "In the previous study, SOD2 deficiency (SOD2+/−) leads to mitochondrial dysfunction, increased mitochondrial DNA damage and accelerated atherosclerosis in ApoE-KO mice." (PMID 26633327, 2015).